FASN (fatty acid synthase)
Diseases named in the same sentence as FASN in open-access papers (continued):
Sharing a sentence is not in itself a finding about the gene and the disease.
tumor (856 papers, 2007 to 2026). "FASN protein is frequently detected in NF2/p16-deficient PM tumor-derived tissues (15/15, 100%), but rarely in NF2/p16-intact PM tumors (8/25, 32%)." (PMID 41764192, 2026). "Overexpression of FASN has been associated with increased tumor aggressiveness, resistance to chemotherapy, and poorer prognosis in NSCLC patients." (PMID 40469185, 2025). "Transcriptional dysregulation of the FASN gene is one of the important mechanisms underlying its overexpression in tumor cells." (PMID 41421797, 2025). "FASN overexpression and hyperactivity are often associated with malignant growth and tumor advancement." (PMID 39963106, 2025). "A pivotal mediator of this enhanced lipogenesis is fatty acid synthase (FASN), an enzyme responsible for catalyzing the synthesis of long-chain fatty acids, whose overexpression has been associated with increased tumor proliferation and poor clinical outcomes." (PMID 41458541, 2025). "Elevated serum FASN levels are associated with tumour extent, lymph node involvement, distant metastasis, and advanced clinical stages." (PMID 41154605, 2025). "Aberrant fatty acid biosynthesis, often driven by upregulation or mutation of FASN, promotes membrane biosynthesis, oncogenic signaling, and lipid-mediated protection from oxidative stress, supporting tumor growth and resistance to apoptosis." (PMID 40873563, 2025). "A murine CRC tumor model was established via subcutaneous implantation of FASN-deficient MC38 cells." (PMID 40148316, 2025). "The activity of SREBP and downstream FASN was found to be up-regulated in tumor-associated Tregs, which contributed to Tregs functional maturation, further correlated with tumor growth and anti-PD-1 immunotherapy inhibition." (PMID 40709184, 2025). "In PDAC, the link between fatty acid synthase (FASN) expression in the tumor stroma is primarily associated with meCAFs (metabolically activated CAFs) rather than the entire CAF population." (PMID 40940809, 2025). "Key biomarkers such as GLUT-1, FASN, and enzymes involved in ferroptosis, cholesterol biosynthesis, and amino acid catabolism demonstrate strong associations with tumor aggressiveness, hypoxia, and mTOR signaling." (PMID 41458541, 2025). "Loss of FASN is sufficient to delay tumor initiation, and this is largely correlated with increased sterol regulatory element-binding proteins (SREBPs) activity, which results in the upregulation of genes involved in DNL and cholesterol biosynthesis." (PMID 38833109, 2024). "Spot 14 which is required for FASN transcription, was reported associating with higher tumor grade, larger tumor size, and poor overall recurrence rates when its expression was upregulated." (PMID 39333940, 2024). "In this study, we identified FASN as a key factor contributing to autophagy in OS and found that elevated FASN expression was associated with a nutrient-deprived microenvironment, tumor malignancy, and autophagy levels." (PMID 39489738, 2024). "Synthesis of new FAs mediated by FASN contributes to the functional maturation of Treg cells, and loss of FASN in Treg cells inhibits tumor growth." (PMID 38581001, 2024). "We found that high levels of FASN were associated with tumor size (P < 0.05), venous invasion (P < 0.05), and direct liver invasion (P < 0.05)." (PMID 39075049, 2024). "Consistent with the in vitro observations, FASN knockdown markedly inhibited tumor growth in mice, which was associated with FSCN1." (PMID 39075049, 2024). "The initial in vivo evidence of tumor growth reduction following FASN inhibition by C75 notwithstanding, it also caused significant weight loss in mice, which constituted its dose-limiting toxicity." (PMID 38672570, 2024). "Attention was then drawn to epigallocatechin-3-gallate (EGCG), the main polyphenolic catechin in green tea, which was reported to inhibit FASN, cause apoptosis in several tumor cell lines in vitro, and shrink tumor diameters in animal models." (PMID 38672570, 2024).
tumor (continued). "Future studies with different experimental designs should examine how FASN loss affects more complex tumor-immune dynamics (e.g., nature of cell-based immunotherapy, heterogeneity of resistant and sensitive sub-populations, etc)." (PMID 39349429, 2024). "The results of the pooled analysis demonstrated that increased FASN expression was associated with large tumor size (odds ratio [OR], 2.04; 95% CI, 1.04-4.00; P = 0.038), HER2 positivity (OR, 1.53; 95% CI, 1.05-2.23; P = 0.028)." (PMID 37124526, 2023). "Further, activation of Akt and ERK1/2 signal transduction pathways regulates tumor-associated FASN gene expression, which confers growth and survival advantages in various tumors." (PMID 37612265, 2023). "As FASN expression is promoted by SREBP-1, they engineered FASN-deficient T-regs cells and observed that these cells were less mature resulting in a decrease of tumor growth." (PMID 36934087, 2023). "This claim is in part supported by two other recent reports where it is shown that KRAS mutated NSCLCs exhibit increased FASN levels and its inhibition results in decreased tumor formation." (PMID 36675307, 2023). "To determine if the increase in FASN expression is important to Cr(VI)-transformed cell tumorigenesis, we examined the xenograft tumor development of Cr(VI)-transformed BEAS-2B cells following the loss of FASN expression using shRNA." (PMID 38069382, 2023). "This study also showed that an inhibition of FASN dramatically inhibits cell proliferation and loss of anchorage independence in Cr(VI)-transformed lung cells and xenograft tumor growth in nude mice." (PMID 38069382, 2023). "FASN is the only cytoplasmic enzyme for the de novo synthesis of lipids and is reportedly associated with tumor proliferation via resistance to radiation and chemotherapeutic drugs." (PMID 36604718, 2023). "FASN upregulation is a common feature of human cancers and their precancerous lesions and is closely associated with chemotherapy resistance, tumor metastasis, and poor patient prognosis." (PMID 37497413, 2023). "We demonstrated by using shRNA knock-down of FASN that FASN is important for Cr(VI)-transformed cell tumorigenesis based on the loss of xenograft tumor growth in nude mice." (PMID 38069382, 2023). "An upregulation of FASN stimulates metastatic tumor cell growth, and FASN overexpression represents a hallmark of invasive tumor phenotypes in human malignancies." (PMID 35954428, 2022). "FASN plays an important role in lipid metabolism and is associated with tumor-related signaling pathways." (PMID 35785165, 2022). "FASN, a key rate-limiting enzyme in the de novo synthesis pathway of endogenous FAs, is associated with multidrug resistance in tumor cells and is an effective target for the treatment of malignant tumors." (PMID 36106108, 2022). "Analysis of RNA-seq data from the CH cohort validated that SREBF1 was associated with FASN, and was differentially expressed in normal and tumor tissues." (PMID 35392075, 2022). "Actually, there are many preclinical and clinical trials in different types of malignancies targeting FASN, but side effects such as drastic weight loss, anorexia, and ineffectiveness in some types of tumours remain a concern." (PMID 36139650, 2022). "FASN is a key enzyme for the de novo synthesis of FA, plays an important role in lipid metabolism, and is associated with tumor-related signaling pathways." (PMID 36452489, 2022). "FASN enzyme plays an important role in lipid metabolism and is associated with tumor-related signaling pathways." (PMID 35785165, 2022). "FASN was differentially expressed in tumor and normal tissues, was associated with tumor grade, and showed prognostic value in both the public and private databases that we studied." (PMID 35392075, 2022). "For highly proliferating cells, tumor-associated FASN is necessary for membrane lipid production and lipid droplet formation to support the increased proliferation and metabolism." (PMID 36307402, 2022).
tumor (continued). "FASN plays a key role in tumor lipid metabolism and is associated with the tumor-associated phosphoinositide 3-kinase (PI3K)/AKT signaling pathway." (PMID 36685937, 2022). "FASN levels are increased in both the tumor tissues and serum of PC patients and are associated with poor prognosis accompanied by low response to GEM." (PMID 36699061, 2022). "Further analyses showed that a favorable tumor immunogenicity and immune microenvironment were involved in FASN mutations." (PMID 36428733, 2022). "Albiges and colleagues tried to explain the paradox in cohorts of metastatic RCC, and found that the fatty acid synthase (FASN) pathway activation is associated with BMI and survival, which is linked to lipogenesis of the tumor." (PMID 35756650, 2022). "GC patients that are positive for FASN had higher tumor stages and a higher risk of distant metastasis." (PMID 34885085, 2021). "In particular, since USP2 modulates the stability of critical tumor-associated proteins such as cyclin D1, Mdm2, and FASN, great efforts have been made to establish a USP2-targeting anticancer drug." (PMID 33530560, 2021). "FASN upregulation in tumor-associated myeloid cells stimulates PPARβ/δ and supports tumor cell invasion." (PMID 33330490, 2020). "Studies have shown that fibroblasts in the tumor microenvironment highly express FASN, which mediates lipid metabolism reprogramming, causes the accumulation of several fatty acids, and promotes the migration of CRC cells." (PMID 33604287, 2020). "In tumor cell lines, FASN overexpression was found to cause chemotherapy resistance induced by culture in drug-containing media." (PMID 33194756, 2020). "Four proteins (FSCN1, SIPA1, SPTBN1 or CD59) closely associated with tumor metastasis interacted with FASN and exhibited decreased expression in response to FASN silencing." (PMID 32699531, 2020). "Elevated expression of fatty acid synthase is associated with tumor invasiveness and poor OS rates in ccRCC patients." (PMID 33221754, 2020). "Analysis of our sequencing data indicated that FASN's relative expression was associated with tumor stage (p = 0.048), and FASN expression was positively associated with the Gleason score (p = 0.004) and seminal vesicle invasion (p = 0.011) in TMA." (PMID 32655718, 2020). "We have previously shown that stable knockdown and pharmacological inhibition of FASN are associated with a decrease in cellular proliferation and tumor growth." (PMID 32850342, 2020). "Overexpression of FASN was also reported to be associated with tumor cell proliferation, metastasis, poor prognosis, and high risk of recurrence in breast cancer, prostate cancer and gastric cancer." (PMID 33194756, 2020). "Blocking FASN activity causes in vitro and in vivo anticancer activity by inhibiting tumor progression, hindering angiogenesis, overcoming drug-resistance, and synergistically increasing the efficacy of chemotherapy." (PMID 30875891, 2019). "Altogether, this body of evidence indicates a unique association between FASN expression and tumor development and/or progression." (PMID 31921669, 2019). "Remarkably, inhibition of FASN by Orlistat in EGFR mutated NSCLC suppresses tumor growth in vitro and in vivo through reducing EGFR palmitoylation but inducing mutant EGFR ubiquitination and subsequent proteasomal degradation." (PMID 29907133, 2018). "The regulation of these processes by tumor-derived FASN-dependent mechanisms provide an opportunity to simultaneously target the multiple immunosuppressive pathways harnessed by tumor-associated DCs." (PMID 30619288, 2018). "In nude mice, fatostatin and luteolin at a doses that effectively downregulate FASN expression caused a marked reduction in tumor growth." (PMID 29968360, 2018). "We observed an inverse association between FASN expression in tumor cells and the infiltration of CD8+ cytotoxic T cells (CTLs)." (PMID 30619288, 2018).
tumor (continued). "Accordingly, FASN expression was negatively associated with tumor grade and vimentin expression, both characteristics described to be closely associated with ML tumors." (PMID 29088795, 2017). "Enhanced FASN expression has been associated with tumor metastasis, chemoresistance and decreased patient survival in many tumors." (PMID 29245936, 2017). "In many tumor types, elevated FASN expression is associated with tumor progression and poor prognosis." (PMID 26709701, 2015). "Conversely, Thrsp loss from MMTV-PyMT mice resulted in slower tumor growth, reduced FASN activity, and lower levels of MCFA compared to controls." (PMID 25472762, 2014). "This differential expression between normal and neoplastic tissues makes FASN a potential diagnostic tumor marker." (PMID 25009654, 2014). "In our previous study, one of these tumor-associated autoantibodies was analyzed and identified as anti-fatty acid synthase (FASN) antibody." (PMID 23128437, 2013). "USP2a, which forms a complex with MDM2, the MDM2 homologue MDMX, FASN (fatty acid synthase), cyclin D1 and Aurora A, is positively linked to tumor progression." (PMID 23236372, 2012). "We made this choice because, more than other proteins in the list, FASN has been associated with tumor progression and because specific inhibitors of FASN are available for further studies." (PMID 20508725, 2010). "Additionally, IHC results revealed a decrease in the expression of proteins associated with fatty acid synthesis, such as SREBF1 and FASN, in tumor tissues after treatment with either CTD or RG3." (PMID 41501793, 2026). "Fatty acid synthase (FASN) is a critical metabolic multi-enzyme in fatty acid synthesis; the up-regulation of fatty acid synthesis caused by the overactivity and expression of FASN provides a nutritional basis for the generation, proliferation and invasion of tumor cells." (PMID 40296917, 2025). "Furthermore, the number of NK cells was significantly higher in the tumor tissue from the FASN-deficient group than in that from the control group." (PMID 40148316, 2025). "Furthermore, lipid accumulation in the tumor microenvironment suppresses T-cell function via palmitoylation of PD-L1, and the activity of FASN/SCD is intricately linked to membrane lipid synthesis and signal transduction." (PMID 40626019, 2025). "Given that FASN gene body hypomethylation was associated with its upregulation in tumor compared with benign tissue, we next queried whether FASN methylation level was correlated with FASN gene or protein expression among primary tumors." (PMID 38112617, 2024). "MSI and tumor mutational load strongly correlated with FASN in a previous study." (PMID 38302980, 2024). "Because tumor cells may be able to compensate for the loss of FASN function in vivo through the utilization of exogenous fatty acids, it was critical for us to determine the effect of diminished FASN function in vivo." (PMID 39149696, 2024). "High levels of FASN are linked to a more aggressive tumor phenotype." (PMID 39609317, 2024). "Accordingly, loss of FASN in Treg cells is sufficient to inhibit tumor growth." (PMID 39349429, 2024). "Additionally, we discovered that in up to fourteen malignancies, FASN expression was significantly associated with tumor immune subtypes." (PMID 36555243, 2022). "Besides, the apoptosis of tumor cells is also attributed to the inhibition of FASN which causes the downregulation of Akt and the starvation of phosphatidylcholine." (PMID 36172157, 2022). "Importantly, an inverse association of FASN expression with Hakai expression was detected in inflammatory AOM/DSS compared to tumour tissue of CAC and healthy tissues." (PMID 36266428, 2022). "Mechanisms underlying HCC inhibition by FASN inhibitors merit further studies to distinguish between indirect effects by reducing the metabolic, inflammatory and fibrogenic drivers of tumorigenesis and direct effects on early tumor cells." (PMID 36123383, 2022).
tumor (continued). "The overexpression of FASN in GC tissues has been linked to shorter survival in bioinformatics studies, and FASN may play a role in tumor formation by controlling macrophage polarization." (PMID 35625633, 2022). "Fatty acid synthase (FASN) is frequently mutated in tumor genomes." (PMID 36428733, 2022). "DAS-induced apoptosis is strongly associated with the down-regulation of FASN in tumor tissues." (PMID 35791446, 2022). "Furthermore, Cav-1, a membrane-associated protein stabilized by FASN by palmitoylation, acts as a tumour-progressing factor, being involved in cancer-drug resistance along with P-glycoprotein (P-gp), a protein that pumps out drugs from targeted cells." (PMID 35334544, 2022). "Similarly, the anti‐tumor effect of EGCG also occurred in parallel with a decrease in FASN levels, which was found to be associated with a decreased level of AKT and ERK1/2 phosphorylation in triple‐negative breast cancer." (PMID 35243817, 2022). "FASN overexpression was correlated with higher tumor stages and a higher risk for metastases in GC." (PMID 34885085, 2021). "A prominent hypothesis suggests that tumor cells with impaired FASN function can compensate for lipid deficiency by importing exogenous lipids and FA from the microenvironment." (PMID 33928023, 2021). "In addition, NAC1 mRNA (which is encoded by NACC1), a transcriptional regulator of FASN in tumor cells, was also increased, as well as PLIN2 (perilipin 2) mRNA, which is involved in lipid droplet formation." (PMID 34206240, 2021). "Interestingly, FASN is upregulated in tumor-associated myeloid cells where it activates nuclear receptor peroxisome-proliferator-activated receptor beta/delta (PPARβ/δ), a key metabolic transcription factor in tumorigenesis." (PMID 33742137, 2021). "Therefore, FASN seems to be highly associated with dissemination processes and tumor aggressiveness, while tumor cells are highly dependent on the “de novo” synthesis of fatty acids by FASN." (PMID 34885085, 2021). "In addition, FASN plays an important role in tumor progression in AIPC, and is one of the causes behind CRPC development." (PMID 33974005, 2021). "Furthermore, conditional deletion of FASN (Alb-Cre; Fasnlox/lox) delays the hepatocarcinogenesis induced by loss of tumor suppressor Pten and overexpression of c-Met and prolongs survival in mice." (PMID 32947972, 2020). "In vivo, inhibition of FASN caused a marked animal tumor weight loss." (PMID 31122252, 2019). "The 3-BP-dependent altered internal milieu in tumor cells could also be linked to the decline of FASN expression, which is suggestive of inhibited de novo fatty acid synthesis, necessary for membrane biogenesis." (PMID 31333455, 2019). "During tumor development, lipid associated alterations include an increase in lipogenic enzymes expression such as fatty acid synthase (FASN), acetyl carboxylase (ACC), stearoyl-CoA desaturase (SCD), ATP citrate lyase (ACLY), and an increase in the synthesis and uptake of cholesterol." (PMID 30913248, 2019). "This time course shows that FASN upregulation is associated with tumor development." (PMID 31676791, 2019). "Finally, we showed that FASN inhibition in PDX tumor tissues is associated with a significant decrease in the pool of adenine nucleotides (AXP) which play a crucial role in a variety of metabolic functions of proliferating cells." (PMID 29872506, 2018). "Moreover, CAPE and CAPPE -mediated suppression of FASN protein was associated with the augmentation of the AMPK cascade in tumor-bearing mice." (PMID 24960186, 2014). "Notably, the FASN inhibitor in combination with the mTOR inhibitor caused tumor regression and induced weight gain in mice bearing ER+/HER2+ tumors." (PMID 24866893, 2014). "Moreover, FA synthesis itself has also been linked to tumour angiogenesis, because treatment with the FASN inhibitor orlistat reduced the formation of lung metastases in a melanoma model." (PMID 24203995, 2013).